KMT2A (lysine methyltransferase 2A)
Diseases named in the same sentence as KMT2A in open-access papers (continued):
Sharing a sentence is not in itself a finding about the gene and the disease.
fibrosis (1 paper, 2025). the formation of excess fibrous connective tissue in an organ or tissue in a reparative or reactive process. "Additionally, by using adeno‐associated viruses with fibroblast‐specific promoters to knockdown KMT2A in mouse lung tissues, we found that bleomycin‐induced fibrosis was alleviated, suggesting that KMT2A in fibroblasts may play a role in lung fibrosis." (PMID 39888275, 2025).
hemophagocytic lymphohistiocytosis (1 paper, 2021). "We report the first case with mutations in FLT3, NOTCH2, and KMT2A, and associated hemophagocytic lymphohistiocytosis." (PMID 34292677, 2021).
Hirschsprung disease (1 paper, 2025). Hirschsprung disease (HSCR) is a congenital intestinal motility disorder that is characterized by signs of intestinal obstruction due to the presence of an aganglionic segment of variable extent in the terminal part of the colon. "Since severe constipation and other GI symptoms are common phenotypes in patients with WDSTS, we stained the distal colon sections of Kmt2a+/+ and Kmt2a+/LSL mice for Calretinin, a clinical diagnostic marker for Hirschsprung’s disease (HD) that marks ganglion cells." (PMID 40956618, 2025).
hydronephrosis (1 paper, 2024). Collection of urine in the renal pelvis that results in dilatation of the renal pelvis and calyces. "Some of the CAKUT cases with associated malformations did reveal a pathogenic variant in WES (unilateral renal agenesis Hypomethylation C2; horseshoe kidney KMT2A; hydronephrosis FREM2, KANSL1; LUTO CHD7; renal hypoplasia GREBIL, POGZ)." (PMID 37535131, 2024).
insulinoma (1 paper, 2023). "This patient’s tumor is the first malignant insulinoma to our knowledge to possess simultaneous mutations in ATRX, ROS1, and KMT2A." (PMID 36835815, 2023).
liver cirrhosis (1 paper, 2025). "An analysis of the clinical liver cirrhosis database revealed that the mRNA expression of Men1 and Setd2 in cirrhotic livers was significantly lower than that in normal livers, whereas the expression of Kmt2a was slightly greater." (PMID 40651612, 2025).
liver fibrosis (1 paper, 2025). "Additionally, KMT2A can target the expression of Caveolin‐1 in liver endothelial cells, playing a role in LPS‐induced liver fibrosis." (PMID 39888275, 2025).
mesenchymal neoplasms (1 paper, 2025). "Recurrent KMT2A and YAP1 related fusions have recently been reported in various mesenchymal neoplasms of different histogenesis." (PMID 40879254, 2025).
metastatic prostate carcinoma (1 paper, 2025). A carcinoma that arises from the prostate gland and has spread to other anatomic sites. "The fusion of ARHGEF12 with histone-lysine N-methyltransferase 2A gene (KMT2A) has been reported in leukemic patients 22, 23, and ARHGEF12 mutations have also been found in metastatic prostate cancer." (PMID 40860157, 2025).
multiple endocrine neoplasia type 4 (1 paper, 2017). Multiple endocrine neoplasia type 4 (MEN4) is a very rare form of MEN, an inherited cancer syndrome, characterized by parathyroid and anterior pituitary tumors, possibly associated with adrenal, renal, and reproductive organ tumors. "The menin/KMT2A complex also regulates the expression of several Hox genes as well asCDKN1B, a gene that harbors inactivating mutations accounting for multiple endocrine neoplasia type 4 (MEN4) syndrome (MIM #610755)." (PMID 28184288, 2017).
oral cancer (1 paper, 2024). "In the nucleus, histone-modifying enzymes, such as SETDB1, SUV39H2, and KMT2A were also associated with areca nuts, suggesting that areca nut-induced mutations also deregulate the expression and silencing of various genes that can promote oral cancer development and progression." (PMID 39027148, 2024).
pulmonary fibrosis (1 paper, 2025). Chronic progressive interstitial lung disorder characterized by the replacement of the lung tissue by connective tissue, leading to progressive dyspnea, respiratory failure, or right heart failure. "The measurement of hydroxyproline concentration indicates that KMT2A knockdown alleviates pulmonary fibrosis in mice compared with the control group." (PMID 39888275, 2025). "The KMT2A transcription complex inhibitor mm102 treatment attenuated bleomycin‐induced pulmonary fibrosis." (PMID 39888275, 2025). "Mice with AAV6‐induced KMT2A knockdown in fibroblast showed attenuated pulmonary fibrosis after bleomycin treatment." (PMID 39888275, 2025). "In summary, we have validated that KMT2A modifies the H3K4me3 on the PU.1 gene promoter region, and treatment with KMT2A inhibitor can alleviate bleomycin‐induced pulmonary fibrosis in mice, indicating the potential of KMT2A to be therapeutic target." (PMID 39888275, 2025). "In this study, competitive inhibitors of KMT2A could reduce PU.1 expression by inhibiting KMT2A complex, and showed therapeutic effects in bleomycin‐induced pulmonary fibrosis in mice." (PMID 39888275, 2025). "We suggested both knocking down KMT2A and inhibiting KMT2A transcription complex could attenuate lung fibrosis, which indicating new therapeutic strategy for clinical practice." (PMID 39888275, 2025). "Moreover, using a competitive inhibitor of KMT2A to prevent complex formation in animal models significantly improved lung fibrosis and injury in mice." (PMID 39888275, 2025). "To validate the specific role of inhibiting the interaction between KMT2A and WDR5 in the development of pulmonary fibrosis, we administered the KMT2A competitive inhibitor mm102 as an intervention treatment in a pulmonary fibrosis mouse model." (PMID 39888275, 2025). "We found that in the bleomycin‐induced lung fibrosis mice model, the levels of α‐SMA and KMT2A were also notably up‐regulated in primary fibroblasts." (PMID 39888275, 2025). "In this study, we report for the first time that the expression of the histone methyltransferase KMT2A is significantly up‐regulated in fibroblasts from both IPF patients and bleomycin‐induced pulmonary fibrosis mouse models." (PMID 39888275, 2025). "KMT2A level was increased in IPF and bleomycin‐induced pulmonary fibrosis mice lung tissues collected in our centre." (PMID 39888275, 2025). "While the role of KMT2A in fibrosis progression has been documented in liver and kidney fibrosis, its involvement in pulmonary fibrosis has not been previously explored." (PMID 39888275, 2025).
rickets (1 paper, 2024). Bone softening and weakening usually caused by deficiency or impaired metabolism of vitamin D. Deficiency of calcium, magnesium, or phosphorus may also cause rickets. "These molecular defects cause abnormal functions of the cartilage extracellular matrix (COMP), paracrine signalling factors (PHEX, FGFR3-related rickets), transcriptional regulation (LZTR1), histone methylation (KMT2A), posttranslational modification (NAA15), and mtDNA replication and repair (POLG)." (PMID 39415983, 2024).
sickle cell disease (1 paper, 2025). Sickle cell anemias are chronic hemolytic diseases that may induce three types of acute accidents: severe anemia, severe bacterial infections, and ischemic vasoocclusive accidents (VOA) caused by sickle-shaped red blood cells obstructing small blood vessels and capillaries.
soft tissue sarcoma (1 paper, 2020). A malignant neoplasm arising from muscle tissue, adipose tissue, blood vessels, fibrous tissue, or other supportive tissues excluding the bones. "Rare soft tissue sarcomas containing KMT2A fusions have recently been reported, characterized by a predilection for young adults, sclerosing epithelioid fibrosarcoma-like morphology, and an often aggressive course." (PMID 32461620, 2020). "We identified 33 (0.2%) soft tissue sarcomas beyond the index case that harbored KMT2A rearrangements." (PMID 32461620, 2020). "This cohort included 15 additional soft tissue sarcomas with complex rearrangements between YAP1 and KMT2A, two soft tissue sarcomas with VIM–KMT2A (patients #S1–S2), and 16 soft tissue sarcomas with KMT2A fusions to unique non-YAP1 non-VIM partners (patients #S3–S18)." (PMID 32461620, 2020).
tauopathy (1 paper, 2025). Neurodegenerative disorders involving deposition of abnormal tau protein isoforms (tau proteins) in neurons and glial cells in the brain. "At the same time, chromatin-modifying enzymes such as KMT2A (MLL1), BRD4, and EP300 are mis-routed in different tauopathy models to either eu-nuclear or nucleolar compartments, which fuel enhanced TWNI productivity into stimulus-responsive enhancers." (PMID 40868276, 2025).
thymic epithelial tumours (1 paper, 2026). "The MAML2 gene fusions (KMT2A::MAML2, YAP1::MAML2, and CRTC1::MAML2), which have been observed in a small subset of thymic epithelial tumours, were not identified in our cohort." (PMID 41344988, 2026).
cancer (240 papers, 2004 to 2026). A tumor composed of atypical neoplastic, often pleomorphic cells that invade other tissues. "KMT2A has been extensively studied for its prominent roles in cancer as well as in brain development, where mutations in the gene KMT2A cause the neurodevelopmental disorder Wiedemann-Steiner Syndrome29,32." (PMID 41279818, 2025). "Menin is a critical epigenetic regulator involved in gene transcription, particularly in cancers driven by KMT2A (also known as MLL1 rearrangements) and NPM1 mutations." (PMID 40723181, 2025). "The hallmark of this cancer is the translocation of the gene encoding MLL (MLL1 or KMT2A) histone methyltransferase with one of more than 80 different partner genes, leading to the formation of oncogenic fusion proteins (MLL-FPs)." (PMID 33477970, 2021). "This suggests that cancer cells are more sensitive than normal cells to the loss of KMT2A activity, which is required to maintain their oncogenic phenotype." (PMID 33302406, 2020). "Originally, the first somatic mutations linked to cancer development were described for the KMT2A gene located on chromosome 11q23, which is rearranged with a considerable number of other translocation partner genes (TPGs)." (PMID 33302406, 2020). "However, we discovered that KMT2A expression was up- or downregulated in several cancer types and that KMT2A expression was linked with a favorable prognosis in certain cancer types (LGG, KIRC, and CHOL), while KMT2A expression was reduced in tumors." (PMID 35058979, 2022). "This indicates that, on the one hand, leukemic transformation can be driven by the GOF KMT2A translocations producing MLL-FPs, while, on the other hand, the development of cancers carrying KMT2A loss-of-function alterations most probably need additional transforming events independent of KMT2A." (PMID 33302406, 2020). "To determine whether susceptibility to hematologic malignancy was affected by the cooperation of Kmt2a-PTD with DNMT3A-WT/MT, we monitored mice up to 10 months." (PMID 32015320, 2020). "MLL1/KMT2A is one of the most frequently mutated genes in cancer." (PMID 28054944, 2017). "Additionally, menin acts as a molecular adaptor, linking KMT2A proteins with LEDGF (lens epithelium-derived growth factor) on cancer-associated target genes, forming the menin–KMT2A–LEDGF complex, which is essential for KMT2A-dependent transcription and leukemic transformation." (PMID 39682203, 2024). "Furthermore, KMT2A expression level was positively associated with cancer invasion and metastasis." (PMID 31090199, 2019). "Revumenib and a second KMT2A-Menin inhibitor, ziftomenib, have also shown efficacy in the treatment of other cancers dependent on KMT2A function, such as NPM1-mutant leukemias." (PMID 41279818, 2025). "It is notable as well that KMT2A and ZMYND11 play opposite and complementary roles in cancer, with ZMYND11 functioning as a tumor suppressor while gain-of-function mutations in KMT2A drive oncogenesis." (PMID 41279818, 2025). "Mitchell and colleagues observed that FOXQ1 binds to RBBP5 in different types of cancer cells, and that it recruits the KMT2A/MLL1 catalytic subunit to the promoters of EMT-associated genes, thereby inducing their transcription." (PMID 39777582, 2025).
cancer (continued). "This review will discuss the current understanding of the multifaceted roles of KMT2A in development and disease, which has paved the way for innovative and upcoming approaches to cancer therapy." (PMID 39303915, 2024). "In different types of cancers, KMT2A acts as an oncogenic factor and plays a significant role in hypoxia signaling, angiogenesis, and tumorigenesis." (PMID 38791111, 2024). "By influencing glycometabolism, KMT2A affects the energy supply and biosynthetic precursors necessary for rapid cancer cell proliferation." (PMID 38791111, 2024). "Genotype–phenotype correlations have been established between KMT2A (11q23.3), KMT2B (19q13.12), KMT2C (7q36.1), and KMT2D (12q13.12) somatic variants and different cancer types." (PMID 36479909, 2023). "We presented a comprehensive characterization of KMT2A, KMT2B, KMT2C, and KMT2D pathogenic variation in a large cancer‐free adult population, with ancestry‐ and sex‐specific frequencies." (PMID 36479909, 2023). "This analysis highlights the pathogenic spectrum of heterozygous KMT2A, KMT2B, KMT2C, and KMT2D mutation found in the gnomAd database, utilizing the non‐cancer adult cohort." (PMID 36479909, 2023). "PROM1 encodes a transmembrane glycoprotein (i.e., CD133) commonly regarded as a cancer stem cell marker and reported to be an important target of KMT2A::AFF1." (PMID 37740239, 2023). "According to the database, among the KMT2A-D proteins, KMT2C is the most frequently mutated (~ 4 050 cases of cancer patients), followed by KMT2D (~ 2 600 cases), KMT2A (~ 1 580 cases), and finally KMT2B (~ 1 250 cases)." (PMID 36598580, 2023). "The expression of most BrD members significantly negatively correlated with cancer stemness across many TCGA tumor types, although only for KAT2B, KMT2A, SMARCA2, BAZ2B, SP100 and SP140, the association was highly consistent (regardless of the tumor type)." (PMID 35049055, 2022). "KMT2A has been researched the most, and there is increasing evidence that it plays a unique function in cancer formation." (PMID 35058979, 2022). "Of the six Compass complexes that can methylate H3K4, KMT2A/MLL1, KMT2C, and KMT2D (MLL3 and 4) have been most widely implicated in cancer." (PMID 35406676, 2022). "Human mutations in MLL1 (KMT2A) and MLL2 (KMT2B) have been associated with cancer and syndromic neurological and psychiatric disorders, such as dystonia, intellectual disability and autism with variable age onsets." (PMID 35223853, 2022). "Interesting approaches to block protein–protein interactions within COMPASS-like complexes for inhibiting cancer growth were also proposed for Menin-KMT2A, and several disruptors such as MI-463, MI-503, and M-525 were described." (PMID 33302406, 2020). "Although KMTs were initially studied for their causative role in hematological malignancies resulting from KMT2A rearrangements, we know today that KMT2C and KMT2D are the most frequently mutated among the human cancer genes." (PMID 33302406, 2020). "Accumulating data demonstrate that KMT2A can play various roles in the development and maintenance of cancers." (PMID 33302406, 2020). "The profiling of cancer mutation genes has identified significant differences in APC, ARIDIA, KMT2A, PIK3CA, and PTEN genes between GC patients of Asian and Caucasian." (PMID 29866191, 2018). "Mutations in other cancer genes including CBFB, IDH1, JAK1, KMT2A, SMAD4, and SMARCA4 were found in one MBC each." (PMID 29214215, 2017).